MYC (MYC proto-oncogene, bHLH transcription factor)
Diseases named in the same sentence as MYC in open-access papers (continued):
Sharing a sentence is not in itself a finding about the gene and the disease.
Burkitt lymphoma (continued). "In P-493 Burkitt’s lymphoma cells, MYC transcriptionally upregulates miR-23b* to decrease the translation of POX/PRODH, leading to the inhibition of proline catabolism." (PMID 32651356, 2020). "The inhibition of LAT1 expression can significantly reduce the growth of Burkitt lymphoma and neuroblastoma cells, suggesting that MYC-induced LAT1 is closely related to tumor cell proliferation." (PMID 33195053, 2020). "Taken together, our studies extend the spectrum of known MYC-induced metabolomic programs and further underscore the role of MYC as the master regulator of metabolic reprogramming in Burkitt lymphoma." (PMID 32138178, 2020). "It is located chromosomally adjacent to and regulates MYC, which in turn is responsible for the majority of Burkitt's lymphoma." (PMID 32602581, 2020). "In Burkitt lymphoma (BL), a chromosomal translocation by which the MYC gene is fused to an immunoglobulin (Ig) gene locus is frequently found." (PMID 31942184, 2020). "A role for MYC in driving human cancer was first identified in Burkitt’s lymphoma, where MYC deregulation was a result of chromosomal translocation into the immunoglobulin heavy chain locus." (PMID 32549409, 2020). "The gene encoding PVT1 is located on the long arm of chromosome 8q24 in a region about 55 kb distal to the MYC gene and, very similar to MYC, is frequently involved in translocations occurring in Burkitt lymphoma." (PMID 33134177, 2020). "As expected, S63845 displayed impressive potency at low nanomolar concentrations in preclinical in vitro and in vivo models of hematological malignancies, including MM, AML, CML and c-MYC-driven Burkitt lymphoma." (PMID 33308268, 2020). "At the cytogenetic level, Burkitt lymphoma is hallmarked by the translocation between MYC (8q24) and IGH (14q32) or less commonly IGK (2p12) or IGL (22q11)." (PMID 33322508, 2020). "This led to the discovery of 13 lncRNAs that were differentially expressed in Burkitt lymphoma carrying the t(8:14) Ig/MYC translocation." (PMID 33134177, 2020). "Subsequently, LAT1- and MYC-knockout Burkitt lymphoma cells were subjected to gene expression profiling." (PMID 33195053, 2020). "In case of Burkitt’s lymphoma, translocated MYC becomes a target of somatic hypermutation (SHM) and activation induced cytidine deaminase (AID) mediated mutational activity." (PMID 32788680, 2020). "For instance, MYC translocations leading to its overexpression are a defining feature of Burkitt lymphoma." (PMID 33051558, 2020). "Similar deregulation of PTEN and MIR17HG is also in place in Burkitt lymphoma (BL) cells, in which the constitute activation of the MYC oncogene that is due to chromosomal translocation also directly activates PI3K/AKT/mTOR." (PMID 32033478, 2020). "Alterations in MYC signaling are hallmarks of many human cancers, such as small cell lung cancer and Burkitt lymphoma, and alterations in the MYC pathway have been observed in ∼30% of cancers with diverse histologies." (PMID 33318047, 2020). "MYC translocation affects several hematological malignancies, including multiple myeloma, Burkitt’s lymphoma, diffuse large cell lymphoma, and T-cell acute leukemia." (PMID 33322239, 2020). "LAT1 and MYC can promote each other's expression and activity in Burkitt's lymphoma and neuroblastoma cells." (PMID 33195053, 2020). "GQC-05 has been shown to down-regulate MYC through G-quadruplex stabilization in Burkitt’s lymphoma cell lines." (PMID 31881855, 2019). "Burkitt Lymphoma (BL) is an aggressive immature B-cells disease, characterized by MYC gene rearrangement, positivity for early B cell markers and a high mitotic rate." (PMID 30704144, 2019). "Burkitt lymphoma is an aggressive subtype of Non-Hodgkin lymphoma driven by the overexpression of MYC." (PMID 31645904, 2019). "Studies have shown that MYC gene alterations are present in nearly 100% of Burkitt lymphoma cases and a minority of DLBCL (3–16%) cases." (PMID 31403034, 2019).
Burkitt lymphoma (continued). "We conclude that high TET1 and low TET2 expression levels in mouse T-ALL and human Burkitt lymphoma-like cells are directly MYC-dependent and are inversed upon MYC inactivation." (PMID 31266538, 2019). "Expression of CDC25B, which is both a MYC target gene in Burkitt lymphoma and necessary for G2/M transition, was decreased upon MB-3 exposure." (PMID 31645904, 2019). "One example is the oncogenic MYC/IGH translocation found in Burkitt's lymphoma and other B cell tumors." (PMID 31275852, 2019). "The enrichment in our study can largely be explained by the fact that, as a reference centre, aggressive and MYC+ DLBCL cases (including suspected cases of Burkitt lymphoma which subsequently prove to be MYC+ DLBCL) are referred to our site." (PMID 31028445, 2019). "Such MYC alterations in myeloma are distinct from other B cell malignancies such as Burkitt lymphomas, where immunoglobulin-MYC translocations are a near universal primary event and IgH-MYC translocations have breakpoints in the IgH switch regions." (PMID 31231360, 2019). "Burkitt lymphoma is characterized by MYC translocation to the immunoglobulin loci resulting in MYC overexpression." (PMID 30874354, 2019). "The large magnitude of these effects was probably due to the large changes in MYC expression explored in these studies: very high starting levels of MYC in Burkitt's lymphoma cells or a complete knockout of MYC in the rat fibroblast cells." (PMID 30909319, 2019). "The cluster is highly expressed in a range of hematopoietic malignancies including MYC-rearranged Burkitt’s lymphomas." (PMID 31581940, 2019). "The compound GQC-05 was shown to stabilize the G-quadruplex in the MYC promoter – among other growth regulatory genes - and also repress its transcription in Burkitt’s lymphoma." (PMID 31881855, 2019). "Our study links MYC to BCR signaling in Burkitt lymphoma through up regulation of SYK transcription by MYC and GCN5." (PMID 31645904, 2019). "MYC overexpression and PI3K signaling have been linked in Burkitt Lymphoma and are both necessary for the survival and fitness of BL cells." (PMID 31645904, 2019). "Burkitt lymphomas are a paradigm of MYC dysregulation, overexpressing MYC due to chromosomal translocation placing the gene under transcriptional control of the immunoglobulin heavy chain enhancer." (PMID 30453475, 2018). "The biopsy confirmed the diagnosis of Burkitt lymphoma with a gene breakpoint on MYC (8q24) determined by FISH." (PMID 30233648, 2018). "We found that inhibition of HSP90 function reduces MYC expression in human Burkitt lymphoma through suppression of MYC transcription and destabilization of MYC protein, thereby diminishing the proliferation of tumor cells." (PMID 30453475, 2018). "To further support the notion that HSP90 stabilizes MYC in Burkitt lymphoma, we combined HSP90 inhibition with inhibition of the proteasome." (PMID 30453475, 2018). "Here, we report that in Burkitt lymphoma the MYC oncogene is a client of HSP90 and can be targeted indirectly through inhibition of the HSP90 machinery." (PMID 30453475, 2018). "In summary, our results show that in Burkitt lymphoma the MYC oncogene is a client protein of HSP90, and that inhibition of HSP90 function with pharmacologic inhibitors caused a switch in MYC transcription as well as MYC protein destabilization." (PMID 30453475, 2018). "In order to determine the effect HSP90 function has on MYC expression in Burkitt lymphoma, we disrupted HSP90 function by using the commercially available HSP90 inhibitor, 17-N-allylamino-17-demethoxygeldanamycin (17-AAG), a derivative of geldanamycin." (PMID 30453475, 2018). "While c‐MYC deregulation is a hallmark of Burkitt lymphoma, synergy between constitutive PI3K/Akt signaling pathway activation and c‐MYC has been shown." (PMID 29522278, 2018). "Another key difference is our use of a Burkitt’s lymphoma cell line (DG75) which carries a MYC translocation." (PMID 30395643, 2018).
Burkitt lymphoma (continued). "We found that inhibition of HSP90 function drastically decreased MYC expression through suppression of MYC transcription and destabilization of MYC protein in human Burkitt lymphoma cell lines." (PMID 30453475, 2018). "Overexpression of the MYC oncogene is a key feature of many human malignancies including Burkitt lymphoma." (PMID 30453475, 2018). "Accordingly, a defect in MYC translation was confirmed in Burkitt’s lymphoma cells and neuroblastoma cells that were null for LAT1 compared with the control cells." (PMID 30103560, 2018). "Consistently, treatment of Burkitt lymphoma cell lines with HSP90 inhibitors (17-AAG or 17-DMAG) was accompanied by downregulation of canonical MYC target genes." (PMID 30453475, 2018). "ChIP-qPCR tiling amplicons for translocated MYC in Burkitt lymphoma were mapped over the immunoglobulin enhancers Eμ, Hs3, Hs12, and Hs4 on chromosome 14 (Amplicons 1–4), as well as, the MYC locus on chromosome 8 (Amplicons 5–14)." (PMID 30453475, 2018). "Using the P493-6 cell line, a model for MYC activation in Burkitt’s lymphoma, total levels of RNA per cell were reported to increase when c-Myc was highly expressed compared to conditions where c-Myc expression was low." (PMID 29313490, 2018). "The findings of a recent study identified that LAT1 and MYC amplify each other’s expression and activity in Burkitt’s lymphoma and neuroblastoma cells." (PMID 30103560, 2018). "To investigate if 17-DMAG is capable of suppressing MYC, we treated Burkitt lymphoma cell lines with 1 μM 17-DMAG over the course of four days." (PMID 30453475, 2018). "In parallel to the switch in MYC transcription, we found that in Burkitt lymphoma cells, MYC is indeed a client protein of HSP90 and HSP90 inhibition affects MYC expression through protein destabilization." (PMID 30453475, 2018). "MYCMI-6 has GI50s as low as 0.5 μM in neuroblastoma and Burkitt’s lymphoma cells with deregulated MYCN/MYC, which is much more potent in comparison to most of the previously reported MYC:MAX inhibitors, such as 10058-F4, 10058-F4 analogues and 10074-G5." (PMID 29968736, 2018). "Direct evidence of involvement of c-Myc in human cancer cells came from the discovery and identification of the c-MYC gene at 8q24 and its translocation onto the immunoglobulin heavy chain locus in human Burkitt lymphoma." (PMID 30053872, 2018). "To investigate the consequence of 17-DMAG treatment on the transcriptional suppression of MYC, we used chromatin immunoprecipitation (ChIP)-qPCR to map histone modifications at the translocated MYC locus in Burkitt lymphoma." (PMID 30453475, 2018). "The inhibition of MYC has been shown to be effective by in vitro studies in MYC-driven cancers such as Burkitt lymphoma." (PMID 29996811, 2018). "Together, we report here the use of HSP90 inhibitors as an alternative approach to target the MYC oncogene and its network in Burkitt lymphoma." (PMID 30453475, 2018). "MYC-activating translocations involving the immunoglobulin loci present in Burkitt’s lymphoma (BL) were once thought to be a product of EBV-mediated re-induction of V(D)J recombination." (PMID 29659614, 2018). "Together, our results show that in Burkitt lymphoma, MYC and HSP90 exist in a complex with each other, suggesting that HSP90 contributes to MYC protein stability." (PMID 30453475, 2018). "We found a significant decrease in MYC mRNA and protein expression in Burkitt lymphoma cell lines treated with 17-DMAG compared to wildtype untreated control." (PMID 30453475, 2018). "Aberrant function of MYC is a feature of about 60% of all human cancers; MYC translocations are present in most Burkitt’s lymphomas and in 5–15% of DLBCL; MYC gains or amplification and rarely MYC translocation were complexively detected in 36% of MCL." (PMID 30038718, 2018). "This is consistent with the notion that constitutively expressed MYC is a major oncogenic driver in Burkitt lymphoma, being required for proliferation and survival." (PMID 30453475, 2018).
Burkitt lymphoma (continued). "To determine if HSP90 physically interacts with MYC in Burkitt lymphoma, we performed co-immunoprecipitation (Co-IP)." (PMID 30453475, 2018). "Jurkat, MOLT-4, P12-Ichikawa and CCRF-CEM (T-ALL), and Daudi and CA46 (Burkitt’s lymphoma) were infected with either a shRNA targeting human MYC (+MYC shRNA)or a scrambled control shRNA (CTRL)." (PMID 29100357, 2017). "In Burkitt Lymphomas, the MYC gene is reciprocally rearranged with the heavy or the light chains of the immunoglobulin (Ig) gene loci." (PMID 28704924, 2017). "Direct evidence of c-MYC’s involvement in human cancer came from the discovery and identification of the c-MYC gene at 8q24 and its translocation onto the immunoglobulin heavy chain locus in human Burkitt lymphoma." (PMID 28379189, 2017). "P493-6 cells carry a tetracycline-repressible ectopic MYC transgene allowing for a range of MYC expression; in the absence of tetracycline the cells express high levels of MYC and display a Burkitt lymphoma-like phenotype." (PMID 28719624, 2017). "An “infamous” example is the MYC/IGH translocations found in Burkitt′s lymphomas in which IGH regulatory elements are misplaced upstream of the MYC proto-oncogene." (PMID 28867784, 2017). "The human c-MYC gene was first revealed in early studies of fulminant chicken tumorigenesis followed by the finding that human MYC is consistently altered by balanced chromosomal translocation in Burkitt lymphoma." (PMID 28422055, 2017). "Consistent with this idea of a negative feedback loop, shRNA-mediated suppression of endogenous MYC was found to up-regulate let-7, whereas let-7 expression was shown to suppress MYC expression in a Burkitt lymphoma cell line." (PMID 26399619, 2016). "Directly, because it is capable of causing deletions or insertions that can lead to oncogenic translocations, such as MYC translocations in Burkitt lymphoma." (PMID 27683157, 2016). "In order to assess POLRMT expression in a variety of cell lines exhibiting endogenous MYC overexpression, the human Burkitt's lymphoma cell line Raji was used in addition to the epithelial line H1299 to represent a lymphoid model with MYC translocation." (PMID 27590350, 2016). "MYC rearrangement, a disease-initiating event in Burkitt lymphoma (BL), can be observed in approximately 10% of de novo DLBCL and correlates with a poorer outcome." (PMID 26573234, 2016). "In vivo studies using a mouse model of Burkitt's Lymphoma provide pre-clinical evidence that these antibiotics can successfully block progression of MYC-dependent tumors." (PMID 27590350, 2016). "This is the case for several translocations, including MYC in Burkitt lymphoma and BCL6 in diffuse-large-B cell lymphoma." (PMID 27683157, 2016). "Because of chromosomal translocations, c-MYC protein is overexpressed in various human tumors, such as promyelocytic leukemia and Burkitt's lymphoma." (PMID 26023799, 2015). "It is known that the hypoxia-inducible factor 1-alpha (HIF1A) and MYC proteins cooperatively regulate expression of the HK2 and PDK1 genes, respectively, in the Burkitt lymphoma (BL) cell line P493-6, carrying an inducible MYC gene repression system." (PMID 26312753, 2015). "A paradigm for MYC dysregulation is offered by Burkitt lymphoma, where chromosomal translocations leading to Immunoglobulin gene-MYC fusion are the crucial initiating oncogenic events." (PMID 26453442, 2015). "JQ1, a chemical compound that inhibits MYC expression is therapeutically effective in preclinical animal models in midline carcinoma, and Burkitt’s lymphoma (BL)." (PMID 24466310, 2014). "The miRs 34B/C have been shown to repress MYC in response to DNA damage, and in Burkitts' lymphoma miR34B/C downregulation was suggested to be a more common mechanism for MYC overexpression than IGH/MYC translocation." (PMID 24722400, 2014).
Burkitt lymphoma (continued). "Most of the cases of Burkitt’s lymphomas presented the MYC translocation at band 8q24 to the Immunoglobuline heavy chain locus (IGH) (14q32) or, less commonly, at the lambda (22q11) or kappa (2p12) light chain loci (IGL)." (PMID 25364378, 2014). "Recently, some Authors have proposed a role for LMP2A early in development of Burkitt’s lymphoma, where the survival signal allows for expansion of cells that contain a MYC translocation." (PMID 25364378, 2014). "Burkitt leukemia/lymphoma (BL) is a highly aggressive subtype of B-cell neoplasm characterized by constitutive MYC expression and PI3K activation." (PMID 23866964, 2013). "Burkitt leukemia/lymphoma (BL) is a highly proliferative B-cell lymphoma characterized by constitutive MYC expression." (PMID 24252186, 2013). "Tetracycline switches off expression of MYC in this Burkitt lymphoma model cell line leading to cell cycle arrest (34, –36)." (PMID 23847767, 2013). "While about 80% of translocations in Burkitt’s lymphoma is typical and involve MYC and IGH@ (IG heavy chain), others are involved in variant partnership with other IG chain loci; kappa light chain (IGK) at 2p12, or lambda light chain (IGL) at 22q11.2." (PMID 23369149, 2013). "Fine needle aspiration showed a high grade B-cell lymphoma, CD10+ (flow cytometry), and the biopsy to the cervical lesion confirmed the diagnosis of Burkitt's lymphoma with gene break point on MYC (8q24) determined by FISH (fluorescent in situ hybridization)." (PMID 23762688, 2013). "Using a murine Burkitt ́s lymphoma model over-expressing human c-MYC, we show here that immunization of mice with human c-MYC protein and c-MYC derived non-homologous peptides elicits a c-MYC-specific CD4+ and CD8+ T-cell response." (PMID 24130880, 2013). "For each staining run we always include reactive tonsil and Burkitt lymphoma with a confirmed MYC translocation to ensure that the antibody and staining platform performs as expected." (PMID 22511926, 2012). "A recent study indicated that miRNA-let-7a inhibits the expression of MYC and reverses MYC-induced growth in Burkitt lymphoma cells." (PMID 22761738, 2012). "Nearly all Burkitt lymphomas (BLs) exhibit elevated MYC protein expression due to transcriptional deregulation following a balanced translocation involving MYC and, most commonly, the immunoglobulin heavy chain locus (IgH)." (PMID 22511926, 2012). "A small subset of DLBCLs has translocations involving the MYC locus and an additional group has a molecular signature resembling Burkitt lymphoma (mBL)." (PMID 22511926, 2012). "Classic examples of recurrent genomic rearrangements in cancer are the BCR-ABL translocation (observed in >90% of cases of chronic myeloid leukemia) and the MYC-IGH fusion (observed in ∼90% of cases of Burkitt's lymphoma)." (PMID 23028501, 2012). "The presence of multiple copies of MYC is compatible with an overexpression of the c-MYC protein, as occurs in Burkitt lymphoma." (PMID 22593768, 2012). "For instance in Burkitt's lymphoma, MYC expression is deregulated through chromosomal translocations juxtaposing MYC and one of the immunoglobulin loci." (PMID 22393362, 2012). "The understanding of MYC biology is of paramount importance to elucidate its role in the pathogenesis of Burkitt lymphoma (BL), a disease characterized by a consistent high MYC protein expression due to a genomic translocation." (PMID 22102868, 2011). "PVT1 was identified as a locus co-amplified with MYC in human Burkitt's lymphomas and found to be a MYC activator." (PMID 21814516, 2011). "Especially Burkitt lymphoma (BL) is a highlight example for MYC overexpression due to a chromosomal translocation involving the c-MYC gene." (PMID 22102868, 2011). "Transfection of let-7 in a Burkitt lymphoma cell line downregulates MYC and reverts MYC-induced cell growth." (PMID 20179807, 2010). "In particular, the stimulated form cooperates with MYC to produce a disease that closely resembles Burkitt lymphoma." (PMID 18578569, 2008).